INS (insulin)
Diseases named in the same sentence as INS in open-access papers (continued):
Sharing a sentence is not in itself a finding about the gene and the disease.
diabetes (continued). "Decrease of circulating insulin in diabetes raises the activity of the enzyme fatty acyl Co-A oxidase that induces beta oxidation of fatty acids, leading to the production of lipid peroxidation." (PMID 26261706, 2015). "Likely explanations are that the Diabetes Consult service reviewed patients in a more timely fashion and also that more physiological insulin regimens were utilized to normalize dysglycaemic results." (PMID 26290664, 2015). "In this study, the number of patients with mitochondrial diabetes using insulin and oral hypoglycemic medications is equal, but the five probands all received insulin treatment at the very beginning of diabetes, which indicated worse beta cell function." (PMID 26449496, 2015). "Intensive lifestyle intervention was more effective than medication in slowing the progression to diabetes, partially due to the fact that lifestyle modifications provide greater improvements in insulin sensitivity and β-cell functions." (PMID 26106625, 2015). "Human insulin is commonly used to treat hyperglycemia in patients with diabetes, but its potential link with female breast cancer is under debate." (PMID 26537234, 2015). "Anti-hyperglycemic medications can effectively reduce blood glucose levels and prevent or forestall diabetes-related complications, yet poor disease control is common, especially when patients’ progressive disease merits the addition of insulin therapy." (PMID 26353820, 2015). "T2D, on the other hand, is mainly caused by the failure of pancreatic β-cells to secrete sufficient insulin to overcome insulin resistance, finally resulting in diabetes." (PMID 26335571, 2015). "In response to STZ-induced (30 mg/kg) diabetes, all groups of diabetic hamsters had a modest reduction in plasma insulin levels and exhibited hyperglycemia (fasting blood glucose ≥12 mmol/L)." (PMID 25884847, 2015). "Although insulin pumps are primarily used for the management of diabetes, their use has also been documented in other conditions such as Addison's disease." (PMID 26089909, 2015). "A variety of basal insulin preparations are used to treat patients with type 2 diabetes mellitus (T2DM)." (PMID 25585592, 2015). "Type 2 diabetes mellitus (T2DM) is a heterogeneous disorder characterized by a progressive decline in insulin sensitivity followed by pancreatic β-cell dysfunction." (PMID 26783461, 2015). "Current diabetes therapies include insulin supplementation and drugs that enhance insulin secretion or tissue responsiveness." (PMID 26384018, 2015). "The variables analysed show significant differences in age, gender, years of diabetes diagnosed, ethnicity, tobacco consumption, pulse pressure, HbA1c, single or combined use of insulin and the prevalence of diabetic retinopathy." (PMID 26464076, 2015). "Diabetes has classically been defined as a group of metabolic diseases characterized by hyperglycemia due to defects in insulin secretion, insulin action, or a combination of both." (PMID 26078998, 2015). "Erectile dysfunction (ED) worsens in patients with diabetes mellitus (DM) despite good control of blood glucose level with insulin." (PMID 25781208, 2015). "Current available therapies for diabetes and diabetic complications include insulin and various oral anti-diabetic agents." (PMID 26468467, 2015). "Hypoglycemia is a major potential adverse effect of diabetes mellitus (DM) treatment with glucose-lowering drugs, such as insulin or oral medications." (PMID 25906112, 2015). "Diabetes mellitus [DM] is a serious chronic metabolic complication that results from abnormal insulin production or metabolism and chronic hyperglycemia." (PMID 26703560, 2015). "The intensive management of Type 1 diabetes mellitus (T1DM) in children requires insulin regimes that are dose adjusted based on the carbohydrate content of a meal and the patient’s blood glucose." (PMID 26636015, 2015).
diabetes (continued). "Infection with S. mansoni cercariae or SEA significantly reduced the spontaneous incidence of diabetes and prevented the class switch from IgM to IgG anti-insulin autoantibodies normally seen in most NOD mice as they approach overt diabetes." (PMID 25879741, 2015). "Diabetes is the most common chronic endocrine disease characterized by hyperglycemia resulted from impaired insulin secretion and/or insulin action." (PMID 26270348, 2015). "Diabetes mellitus can be defined as a group of metabolic diseases characterized by chronic hyperglycemia resulting from impaired insulin action/secretion and is classified into two major categories, type 1 and type 2." (PMID 25561919, 2015). "It is well recognized that impaired first-phase insulin secretion is an early marker of β-cell dysfunction, and also an independent and additive predictor of the progression of diabetes." (PMID 25574243, 2015). "In permanent neonatal diabetes (PNDM) patients, homozygous GCK (n=6), EIF2AK3 (n=3), PTF1A (n=3), and INS (n=1) and heterozygous KCNJ11 (n=2) mutations were identified." (PMID 25755231, 2015). "As such, activation of S1P has been shown to be critical in protecting pancreatic β-cells (the cells that produce, store, and release insulin) from apoptosis and preventing the development of diabetes in obese mice." (PMID 25866760, 2015). "The mean duration of diabetes was 10.1 ± 8.6 years; 85.5% of the patients were using oral antidiabetic agents and 30.9% were taking insulin injections, alone or combined with oral antidiabetic therapy." (PMID 25885487, 2015). "The mean duration of diabetes at baseline was 6.9 years; 95% CI [6.2, 8.0] and 27%; [21, 35%] had insulin treatment." (PMID 26216409, 2015). "Aw & Cheah showed that AA totalis, which developed simultaneously with diabetes mellitus, was improved after insulin therapy, indicating that the recovery from metabolic disturbance was involved in regrowth of the hair." (PMID 25759758, 2015). "Type 2 diabetes mellitus (T2DM) is the most prevalent metabolic disorder that is characterized by insulin insensitivity as a result of impaired insulin secretion, insulin resistance, and eventual pancreatic beta-cell failure." (PMID 26267061, 2015). "The average period of insulin treatment and the proportion with long-standing diabetes (>5 years) were significantly increased in BOT users compared to CT or SIT (both p<0.05)." (PMID 25698911, 2015). "A driver with insulin-treated diabetes needs to have accurate knowledge of their blood glucose, and appreciate the minimum level compatible with safe driving." (PMID 28702227, 2015). "Type 2 diabetes (T2D) is a chief form of DM which results from the body’s ineffective use of insulin, it comprises 90% of people with diabetes around the world." (PMID 26406581, 2015). "Intensive insulin therapy using basal-bolus insulin regimen is the standard therapy for patients with type 1 diabetes mellitus." (PMID 26435713, 2015). "Diabetes refers to a group of metabolic diseases characterized by hyperglycemia resulting from defects in insulin secretion, insulin action, or both." (PMID 25774817, 2015). "The drugs showing potential for the cure of diabetes have been used singly and also in combination of multiple oral agents and with addition of insulin but achieving the complete glycemic control is a challenging task." (PMID 26273667, 2015). "We consider that the improvement of insulin sensitivity by liraglutide would be useful and beneficial in investigating the fundamental pathophysiology of diabetes." (PMID 25922845, 2015). "Diabetes induction significantly increased the insulin level in the T2D group compared with the CTR group." (PMID 26185997, 2015). "In recent years, the influence of vitamin D on diabetes becomes a research hotpot; many studies paid attention to the relationship between vitamin D and insulin sensitivity and β-cell function." (PMID 25741510, 2015).
diabetes (continued). "People using insulin for treatment of their diabetes had tendency to suffer from depressive symptoms 2.3 times higher than people on medication." (PMID 26236749, 2015). "Diabetes mellitus (DM) is characterized by insufficient production of insulin (type 1) or, more commonly, inefficient insulin signaling pathways (type 2), a state known as insulin resistance (IR)." (PMID 26578976, 2015). "Despite the risks associated with hypoglycemia and driving, several surveys have shown that drivers with insulin-treated diabetes continue to embrace unsafe practices." (PMID 28702227, 2015). "Although insulin therapy is widely used for management of diabetes mellitus, its many side effects such as, insulin resistance, anorexia nervosa, brain atrophy, and fatty liver after chronic treatment makes it a risky proposition." (PMID 26490765, 2015). "Because Wnt3-induced NeuroD1 is a critical factor for neurogenesis and pancreatic development, it is suggested that the cognitive deficit and impairment of insulin secretion in diabetes, AD, and HD are due to the impairment of Wnt3-induced NeruoD1 activity." (PMID 26075247, 2015). "Insulin requirements of diabetes patients decrease as renal disease progresses, due to reduced insulin degradation in the kidney." (PMID 25721247, 2015). "The authors therefore concluded that diabetes developed as a consequence of the strong decrease in pancreatic insulin content that they clearly observed by 3 weeks after tamoxifen treatment." (PMID 26038943, 2015). "Main therapies for diabetes aimed indeed at restoring insulin levels either by stimulating insulin secretion or improving insulin sensitivity." (PMID 26406981, 2015). "The workshop comprised a mixture of lectures on diabetes, pharmacotherapy, dietary management [...]; insulin injection technique and devices; and blood pressure measurement”." (PMID 25900104, 2015). "Diabetes implications: Phentermine-topiramate use is associated with improvements to numerous glycaemic markers such FBG, fasting insulin, glycated haemoglobin (HbA1c) and homeostatic model assessment of insulin resistance (HOMA-IR)." (PMID 25894803, 2015). "In the last two decades, diabetes management has undergone paradigm shifts with increased public health education, improved insulin delivery methods, better targeting of oral hypoglycaemic agents and more intensive monitoring." (PMID 26715333, 2015). "Rosiglitazone is a well-known insulin sensitizer, and as such has been used for the treatment of type 2 diabetes mellitus." (PMID 26418009, 2015). "In relation to those on insulin as a diabetes treatment regime, the prevalence was 0.52 (95% CI 0.37 to 0.67) compared with 0.33 (95% CI 0.24 to 0.42) for sulphonylureas." (PMID 26061690, 2015). "Melatonin seems to have a stronger effect on rhythmicity, while insulin seems to act both on the metabolic and chronobiological effects of diabetes." (PMID 25960780, 2015). "Maturity onset diabetes of the young (MODY) and neonatal diabetes mellitus (NDM) represent two different classes of monogenic diabetes where hyperglycemia is either due to defects in insulin secretion, decrease in beta cell mass or both." (PMID 26300908, 2015). "The aim of this randomized controlled trial (RCT) is to evaluate the effectiveness of an MTH intervention on adults with insulin-requiring diabetes." (PMID 25803226, 2015). "The importance of kinase signaling in diabetes and related disorders is further illustrated by anti-diabetic drugs, such as thiazolidinediones and metformin, that facilitate glucose transport and insulin response through promoting insulin signaling." (PMID 26202599, 2015). "The subsample of participants recruited through CWD had higher household income, duration of diabetes, and greater insulin pump use." (PMID 26715191, 2015). "The intervention was to allow eligible inpatients to manage their own basal-bolus insulin regimen with support from diabetes nurse practitioners (DNPs)." (PMID 26429339, 2015).
diabetes (continued). "In rats, diabetes leads to hypothermia and reduced melatonin synthesis; insulin treatment reestablishes both." (PMID 25960780, 2015). "Among patients with diabetes, 24.2 % (n = 16) were on a combination of Glibenclamide and Metformin while 22.7 % (n = 15) used both metformin and Insulin." (PMID 28702226, 2015). "Although, both of above processes result in an increase in insulin sensitivity, effect of chromium on insulin resistance in subjects with diabetes and MetS is controversial." (PMID 26157708, 2015). "In people with type 2 diabetes (the most common type of diabetes), blood sugar control fails because the fat and muscle cells that normally respond to insulin by removing excess sugar from the blood become less responsive to insulin." (PMID 25992895, 2015). "Nevertheless the fact that all but seven patients in the Melioid Cohort population with pre-diagnosed diabetes were receiving drug therapy, including insulin in the majority of cases, is evidence of receiving diabetes care." (PMID 26495852, 2015). "It was concluded that ZnONPs either alone or in combination with insulin have the ability to increase the sperm count and motility and protect the testicular tissue against the oxidative stress induced by diabetes in rats." (PMID 26581756, 2015). "Patients with diabetes on insulin therapy encounter multiple obstacles when performing self-management behavior." (PMID 25340869, 2014). "Studies on cells in vitro, experimental animal model of diabetes and with human patients showed that a single bout of exercise increased the insulin sensibility." (PMID 24728251, 2014). "Several studies indicate that diabetes leads to impaired fracture healing, and this abnormal repair is insulin-dependent, because it was reversed by insulin treatment." (PMID 24651693, 2014). "The results also imply that saponins from S. chinensis can enhance glucose uptake and insulin sensitivity, representing a promising treatment for type 2 diabetes mellitus." (PMID 24918297, 2014). "Given limited access to specialist resources and the size of the diabetes epidemic, primary care is where insulin initiation must become part of routine practice." (PMID 24528528, 2014). "The HMW adiponectin is the main active form of the hormone and has relevant role in enhancing insulin sensitivity and protecting against diabetes." (PMID 24650537, 2014). "Diabetes mellitus (DM) is a heterogeneous group of metabolic disorders characterized by hyperglycemia stemming from defects in the secretion and/or action of insulin." (PMID 24716713, 2014). "We showed that at early stages of diabetes, vascular damage occurs in the endoneural space of the renal nerves that increase in severity on chronic diabetes regardless insulin treatment." (PMID 24387617, 2014). "Insulin administration prevented the diabetes-induced increase in the serum and urine ACE2 activity in the NOD mice." (PMID 24400109, 2014). "It should be noted, however, that IGT does not distinguish between risk of T2DM and early, pre-clinical signs of Type 1 diabetes mellitus (T1DM), which results in elevated post-glucola BG due to insufficient insulin secretion." (PMID 24755002, 2014). "Activation of the glucagon-like peptide-1 receptor (GLP-1R) in pancreatic β-cells potentiates insulin production and is a current therapeutic target for the treatment of type 2 diabetes mellitus (T2DM)." (PMID 25180755, 2014). "For example relationships between vaspin and parameters of insulin sensitivity were significantly altered by the diabetes state in obese individuals." (PMID 24968098, 2014). "These investigations should include analysis of diabetes duration, duration of insulin treatment, insulin dose, age, gender, and BMI." (PMID 25593947, 2014). "Alloxan prompts diabetes by destroying the insulin secreting cells of the pancreas resulting in hypoinsulinemia and hyperglycemia." (PMID 25114914, 2014).
diabetes (continued). "A recent review based on a MEDLINE search of studies relevant to Technosphere insulin concludes that it is has a pharmacokinetic profile suitable to meet prandial insulin needs in patients with diabetes." (PMID 25505695, 2014). "She had chronic recurrent pancreatitis and developed new onset of diabetes after transplantation (NODAT) requiring insulin." (PMID 24902943, 2014). "In the Fourth Korea National Health and Nutrition Examination Survey (KNHANES), a low serum 25(OH)D level was associated with fasting insulin, HOMA-IR, and diabetes." (PMID 25514561, 2014). "Insulin treatment is the inevitable choice for people with type 2 diabetes (T2DM) as diabetes progresses." (PMID 25424627, 2014). "Patients of Group 1 who saw no added value of using such a system typically felt confident to perform insulin titration themselves, or were content with current diabetes management practice." (PMID 25340869, 2014). "Development of insulin resistance with obesity, pre-diabetes, and type 2 diabetes is a physiopathologic process where cells fail to respond normally to insulin." (PMID 25486190, 2014). "For instance, a region with a high proportion of diabetes patients on insulin treatment is expected to result in a higher contract price than a region with a low proportion of these patients." (PMID 25359224, 2014). "The opposing enzyme which phosphorylates glucose, that is,hexokinase, is unaffected by insulin and decreases in diabetes." (PMID 24800231, 2014). "Diabetes is a chronic metabolic disorder characterized by hyperglycemia which results from insufficient insulin level or unresponsiveness of target cells to insulin action." (PMID 24988468, 2014). "In Australia, the Fremantle Diabetes Study, reported a median HbA1c of 9.4% prior to insulin commencement." (PMID 24886287, 2014). "A large amount of VAT leads to adipose tissue dysfunction followed by impaired insulin sensitivity, secretion of pro-inflammatory adipokines, and ultimately type 2 diabetes mellitus (DM), left ventricular dysfunction, and coronary artery disease (CAD)." (PMID 24624968, 2014). "Type 1 diabetes mellitus (T1D) is an autoimmune disease characterized by insufficient insulin secretion and progressive damage of islet β-cells." (PMID 24663217, 2014). "Diabetes is characterized by hyperglycaemia due to impaired insulin secretion and aberrant glucagon secretion resulting from changes in pancreatic islet cell function and/or mass." (PMID 25145789, 2014). "Many patients with type 2 diabetes mellitus (T2DM) ultimately require insulin to maintain glycaemic control." (PMID 25048824, 2014). "Increased oxidative stress contributes to the development and progression of diabetes and chronic oxidative stress results in decreased responsiveness to insulin, ultimately leading to type 2 diabetes." (PMID 24502834, 2014). "Although insulin therapy and hypoglycemic drugs can control blood glucose levels quickly and effectively and the mortality of acute complications due to diabetes also has been basically controlled, the chronic complications of treatment are inadequate." (PMID 24633252, 2014). "This technique represents a promising strategy to promote the intestinal absorption efficiency of the hormone, enabling an efficient route for oral delivery of insulin for diabetes management." (PMID 24833901, 2014). "Among patients who developed hyperglycemia, 100% of those who required insulin were in the 13 to 18-year age group and reported a family history of diabetes." (PMID 24734157, 2014). "This highlights the need for the application of more sophisticated and reproducible methods to explore the dynamic relations between glucose and insulin in patients with diabetes, especially in those managed with incretin-based therapies." (PMID 24524730, 2014). "Diabetes mellitus type 2 (T2DM) accounts for almost 90% of diabetes cases, with the property of insulin resistance and beta-cell dysfunction that induces hyperglycemia." (PMID 25574393, 2014).